JUP (junction plakoglobin)
Diseases named in the same sentence as JUP in open-access papers (continued):
Sharing a sentence is not in itself a finding about the gene and the disease.
cancer (30 papers, 2012 to 2025). A tumor composed of atypical neoplastic, often pleomorphic cells that invade other tissues. "The expression of different catenin molecules in different cancer tissues was inconsistent, and several molecules, including PKP3, PKP2, PKP1, and JUP, were overexpressed in several cancer tissues." (PMID 37924160, 2023). "JUP is an adhesion protein; thus, insufficient expression of JUP reduces cell–cell contact and increases the invasion and spread of cancer cells in the body." (PMID 37328487, 2023). "Junction plakoglobin is a cell adhesion protein, and its defective expression reduces cell‐to‐cell contact and promotes migration of cancer cells in vivo." (PMID 36036768, 2022). "Pathway of pathways in cancer was enriched in 8 DEGs, such as junction plakoglobin (JUP) and epidermal growth factor receptor (EGFR)." (PMID 33178610, 2020). "JUP is a component of desmosomes and is less expressed in cancer with respect to normal prostate tissue." (PMID 22328933, 2012). "In cancer, JUP is involved in mediating the cell cytoskeleton actin." (PMID 40431638, 2025). "As JUP encodes a protein involved in cell–cell contacts, this might suggest a role for this process in OAC cancer cell survival and a potential route to therapy." (PMID 36803948, 2023). "In addition, we also detected multiple PUD risk, cancer-related genes (for example, IHH, GNAS, NHEJ1, JUP and MECOM), which provided potential targets contributing to the different outcomes of PUD or GC." (PMID 38036781, 2023). "Moreover, JUP strongly activates c-Myc and cyclin D1 expression and supports cancer progression by mediating survival through the inhibition of apoptosis and promotion of cellular proliferation." (PMID 38203664, 2023). "IHC analysis underlined that JUP protein expression was higher in the entire epithelial layer of cancer tissue compared to adjacent normal samples, suggesting that JUP could be a good candidate for the treatment of CRC." (PMID 38203664, 2023). "JUP overexpression was reported in many cancers, where it may act as an oncogenic or tumor suppressor protein." (PMID 37834160, 2023). "The role of junction plakoglobin (JUP) during cancer progression is still controversial." (PMID 36387263, 2022). "So, we hypothesized that cancer stem cells maybe essential in the regulatory mechanism of JUP and ITGB4." (PMID 34402716, 2021). "While Program-1 was enriched with genes from a pan-cancer EMT program, it also notably included epithelial differentiation genes such as CDH1, IRF6, JUP, KLF6, and TJP2." (PMID 40777467, 2025). "Among these are enhancers for JUP, MYBL2, and CCNE1, and we show that their activity is required for cancer cell viability." (PMID 36803948, 2023). "At the pan-cancer level, most signaling pathways, particularly PKP4, PKP2, JUP, and CTNND2, showed high levels of activation in the Hormone AR signaling pathway, but consistent inhibition of apoptosis, cell cycle, and DNA damage responses." (PMID 37924160, 2023). "RALGPS1, NUDT9, NUDT2, and PDE4A were less expressed in cancer cell lines; JUP, ADA, HPRT1, and IMPDH1 were highly expressed in cancer cell lines in CCLE." (PMID 34745385, 2021). "In the CCLE database, expression of JUP, ITGB4, ST8SIA5, ST8SIA1, ST3GAL2, ST3GAL5 and B4GALNT1 in pan-cancer were explored." (PMID 34402716, 2021). "And the results showed a higher expression of JUP and ITGB4 in cells expressing CD44 or CD24, which were cell markers of cancer stem cells." (PMID 34402716, 2021). "The association of high JUP protein expression and biochemical recurrence was mainly driven by the subset of TMPRSS2:ERG fusion‐negative cancers (P = 0.0003) and not seen in the ERG fusion‐positive subset (P = 0.258)." (PMID 33533127, 2021).
cancer (continued). "The combined analysis of RNA-seq and ChIP-seq for H2A.Z showed downstream gene regulation to mainly occur via the transcriptional misregulation in the cancer pathway, its target genes mainly including TCF3 CDK14, JUP, SPINT1, CDKN1A, and IGF1, each of which corresponded to different cell phenotypes." (PMID 34120148, 2021). "Since JUP is an adhesive protein, the lack of JUP expression can reduce cell–cell contact and increase its proliferation in the body and cancer cells." (PMID 34402716, 2021). "In particular, the pathway of pathways in cancer was enriched by 8 DEGs, such as EGFR and JUP." (PMID 33178610, 2020). "In addition, we found that acetylation of H2A.Z in HCC could change the chromatin status and promote the transcription of downstream genes, including TCF3, CDK14, JUP, SPINT1, CDKN1A, and IGF1, which are important regulatory molecules in the cancer misregulation pathway." (PMID 34120148, 2021).
infection (4 papers, 2013 to 2025). The state of being infected such as from the introduction of a foreign agent such as serum, vaccine, antigenic substance or organism. "Notably, JUP deficiency resulted in significantly lower levels of IL-1rα, IL-12 (p70), MIP-1α, MIP-1β, RANTES, and TNF-α at 15 h post-infection, compared to siCN-treated cells, supporting the importance of JUP in RSV-induced cellular responses." (PMID 40431638, 2025). "Of the 227 BRD4 interactors that were recruited to the BRD4 complex during RSV-infection, we observe that 95 ( 42%) are disrupted to some degree by treatment with ZL0454, including most of the transcription factors described in the earlier section (e.g., c-JUN, CTNNB1, JUP, DDX3X, MTDH)." (PMID 33799525, 2021).
cardiac disease (2 papers, 2020 to 2022). "A substantial number of genetic variants in the genes DSP, JUP, DSC2, KLHL24 and GJA1 have been reported to underly skin and/or cardiac disease." (PMID 36142674, 2022).
cardiovascular disease (2 papers, 2012 to 2022). "We screened 404 genes related to inherited cardiovascular disease and confirmed that no deleterious mutations were present in other desmosomal genes, including DSC2, DSG2, JUP, and DSP, involved in the etiology of AC." (PMID 35063130, 2022).
JUP also shares sentences with these, for which no sentence is quoted: acute myeloid leukemia (3 papers); lung adenocarcinoma (3); bacterial infections (2); cardiac arrhythmia (2); ectodermal dysplasia (2); ovarian cancer (2); Palmoplantar keratoderma (2); acute coronary syndrome (1); autosomal recessive congenital ichthyosis (1); benign prostatic hyperplasia (1); bladder tumor (1); breast invasive carcinoma (1); Brugada syndrome (1); Carvajal syndrome (1); cortical dysplasia (1); dyskeratosis congenita (1); Dystonia (1); epilepsy (1); Epileptic encephalopathy (1); frontotemporal dementia (1); genetic disease (1); hypertrophic cardiomyopathy (1); ichthyosis vulgaris (1); Immunodeficiency 50 (1); infectious disease (1); Insulin resistance (1); keloid (1); keratolytic winter erythema (1); Lewy Body Disease (1); Long QT syndrome (1).
A further 16 diseases each share a sentence with JUP in 1 paper.